HGF (hepatocyte growth factor)
Diseases named in the same sentence as HGF in open-access papers (continued):
Sharing a sentence is not in itself a finding about the gene and the disease.
cancer (continued). "Then, the upregulated paracrine HGF binds the c-MET receptor on the migrated cancer cells to facilitate the seeding and proliferation of metastatic cancer cells." (PMID 30925929, 2019). "Increasing evidence demonstrates that abnormal activation of HGF/c-MET was involved in the cancer progression." (PMID 31426831, 2019). "Previous studies have shown that cancer-associated fibroblasts (CAF) secrete a variety of cytokines in and high levels of growth factors such as EGF, TGF-β, HGF, and FGF-2 into CAF-conditioned media." (PMID 31491033, 2019). "Various signaling pathways (e.g., VEGF, EGF, FGF, and HGF) are significantly included in cancer tissue angiogenesis and ensure the heterogeneity of blood vessel structures." (PMID 30970626, 2019). "Hepatocyte growth factor (HGF) and its receptor, c-Met, have been shown to play an important role in cancer angiogenesis." (PMID 31331111, 2019). "Metastasis of cancer cells is closely associated with angiogenesis stimulated by angiogenic activators such as PDGF-BB, TGF-β1, FGF, HGF, NOS, COX-2, IL-5, and VEGF." (PMID 30949393, 2019). "Hepatocyte growth factor (HGF) is a paracrine growth factor known to contribute to cancer progression." (PMID 31106200, 2019). "Activation of c-Met in cancer cells by its natural ligand, the hepatocyte growth factor (HGF), accelerates proliferation, scattering, migration, invasion, and metastasis." (PMID 30781364, 2019). "Through the generation of mouse models, it was possible to demonstrate that this protease regulates cancer cell invasion and metastasis to distant organs through activation of the Hepatocyte Growth Factor/c-met axis." (PMID 31366128, 2019). "We also found that sorafenib treatment downregulated cancer cell proliferation; and this was significantly prevented in the presence of HGF." (PMID 30647407, 2019). "In gastic cancer cells HGF can induce MMP-9 through upregulation in lipocalin-2 and activation of NFκB39." (PMID 30631034, 2019). "HGF/c-Met signal, as a couple of ligand and receptor, plays a major role in progression among multiple cancer types." (PMID 30886866, 2019). "Cellular mesenchymal-to-epithelial transition factor (c-MET), affecting cancer cell morphogenesis, angiogenesis, and cytoprotection in vitro, is a high-affinity receptor for binding to hepatocyte growth factor (HGF)." (PMID 29187584, 2019). "We explored the impact of exogenous HGF on sensitivity to c-Met inhibition in several cancer cell models." (PMID 30719213, 2019). "Stromal fibroblasts critically contribute to CRC tumorigenesis by producing hepatocyte growth factor (HGF) to establish the cancer stem cell phenotype and TGFβ treatment activates fibroblasts to enhance metastasis, partially via IL-11." (PMID 31028424, 2019). "In cancer cells, HGF activates downstream RAS/MAPK and PI3K signaling pathways by binding to its receptor MET." (PMID 31106200, 2019). "In the context of this pathologic liaison, cancer cells stimulate PSCs to secrete growth factors such as HGF, and in turn HGF and probably other factors secreted by these stromal cells induce proliferation and drug resistance in PDAC cells." (PMID 31072019, 2019). "Aberrant HGF/Met signaling has been shown to promote cancer cell invasion and metastasis in diverse cancer including oral squamous cell carcinoma (OSCC)." (PMID 31533338, 2019). "The binding of active HGF to c-MET activates signaling cascades leading to cancer progression, invasion, and metastasis." (PMID 30669409, 2019). "Dysregulation of HGF/c-Met axis promotes acquired resistance to cancer cells treated with HER family targeted therapies." (PMID 30781364, 2019). "c-Met is predominantly expressed in epithelial cells (including carcinoma cells), hepatocytes, and endothelial cells, and HGF expression is limited by mesenchymal cells, such as fibroblasts and muscle cells." (PMID 30658428, 2019).
cancer (continued). "The growth factors secreted by fibroblasts also showed to be central for creation of a favourable milieu for cancer development, especially HGF (hepatocyte growth factor) and its signalling pathway through c-Met activation." (PMID 29976244, 2018). "In malignant tumors, HGF is primarily expressed and released by surrounding stromal cells, including CAFs and TAMs." (PMID 30352967, 2018). "Both HGF and c-Met are upregulated in different types of human cancers such as breast, lung, colorectal, gastric, and oesophageal cancer." (PMID 30186533, 2018). "The significance of HGF activity in cancer development and progression has also been confirmed through clinical studies; where the degree of HGF and c-Met expression was found to correlate with disease progression and poor patient prognosis." (PMID 30314527, 2018). "Having shown that fibroblast miR-16 levels slightly affect the proliferation capacity of adjacent cancer cells and can strongly influence their migration, we investigated the relevance of the miR-16/HGF axis in vivo." (PMID 29558956, 2018). "This suggested profound implications considering the potential paracrine effect of HGF on surrounding cancer cells in the TME." (PMID 29558956, 2018). "We identified miR-16 as a master regulator of fibroblast secretome and showed that its upregulation reduces HGF secretion by fibroblasts, impairing their capacity to promote cancer cell migration." (PMID 29558956, 2018). "Researchers have reported that the activation of HGF/c-Met signaling in cancer cells promoted VEGF biosynthesis in a PI3K signaling pathway-dependent manner." (PMID 29416603, 2018). "It has been shown that HGF is able to increase this function, thus suggesting a positive role in anti-cancer immunity." (PMID 30441809, 2018). "Unfortunately, the same highly regulated events that mediate MET/HGF biological responses during embryo development and contribute to maintain tissue homeostasis in the adult are unleashed in cancer." (PMID 30544501, 2018). "Upon complexing with its specific receptor c-Met, HGF evokes an array of biological responses within cancer cells, which subsequently lead to enhanced cell migration, matrix degradation, invasiveness and induction of angiogenesis." (PMID 30314527, 2018). "Hepatocyte growth factor (HGF) induces a MET-AXL-ELMO2-DOCK180 complex that activates Rac1-dependent cancer cell migration and invasion." (PMID 30261690, 2018). "Specifically, in the context of cancer, the role of HGF/MET is very complex: HGF is secreted by cancer cells themselves, and also by stromal cells." (PMID 30441809, 2018). "The same MET/HGF-dependent mechanism described in a physiological context is exploited by cancer cells to disseminate from the tissue of origin and to colonize a different organ." (PMID 30544501, 2018). "Hepatocyte growth factor (HGF) plays an important role in cancer progression via phosphorylation of MET (c-met proto-oncogene product, receptor of HGF)." (PMID 30469509, 2018). "We find that cancer cells driven by METamp are more sensitive to INC280 than are those driven by HGF-autocrine activation." (PMID 30208970, 2018). "In the present study, we evaluated the HGF, which is activated in an autocrine manner, and the anti-cancer effects of foretinib using in vitro and in vivo experimental models." (PMID 29854314, 2018). "Several reports review the clinical trials that are presently evaluating the benefit of anti-c-Met and anti-HGF monoclonal antibodies and tyrosine kinase inhibitors in a variety of cancer types including TNBC." (PMID 30314527, 2018). "Early findings postulated that the osteoblast, bone marrow precursor cells in bone marrow microenvironment tend to produce substances for instance HGF which further promotes cancer cell proliferation and migratory activities." (PMID 29455663, 2018).
cancer (continued). "Abnormal stimulation of the HGF/c-Met (cellular mesenchymal to epithelial transition factor) pathway has a remarkable role in the progression of various models of cancers as well as advancement of tumor invasion and metastatic system." (PMID 29301373, 2018). "This review focuses on understanding how the ECM can influence the HGF/c-MET signaling pathway during cancer progression." (PMID 30352967, 2018). "Hepatocyte growth factor (HGF) is able to induce epithelial–mesenchymal passage in cancerous cells which can result in cancer cell migration." (PMID 29301373, 2018). "The malignant behavior of cancer cells is nurtured by the collateral pro-angiogenic activity of the MET/HGF axis in endothelial (ECs) and stromal cells." (PMID 30544501, 2018). "It has been shown that cancer-associated fibroblasts promote cell scattering, epithelial-mesenchymal transition (EMT), and migration of cancer cells in an HGF-dependent manner." (PMID 30186533, 2018). "Stromal cells influence the action of cancer therapeutics, and stromal changes such as release of HGF can provide an alternate stimulus when other pathways are blocked." (PMID 30134579, 2018). "HGF is known to promote proliferation, migration, invasion and survival of cancer cells, and to confer resistance to therapy." (PMID 30214428, 2018). "The HGF/c-Met axis has been targeted in several ways for potential cancer treatment, including targeting receptor activation and ligand binding." (PMID 30134579, 2018). "HGF is an important component of the fibroblast secretome, and has been shown to stimulate cancer cell invasiveness, and promote the epithelial-mesenchymal transition (EMT), cell scattering and migration." (PMID 30214428, 2018). "In this context, microenvironment-derived HGF plays a pivotal role in cancer cell resistance to therapy, sustains cancer stem cells, and promotes invasive growth and dissemination." (PMID 29558956, 2018). "In cancer patients, high serum levels of HGF correlated with high neutrophil counts and poor responses to checkpoint blockade therapies." (PMID 30400835, 2018). "In various solid tumors, including gastric, breast, thyroid and hepatocellular carcinomas, the HGF/c-Met pathway was detected as a critical in cancer development." (PMID 29455657, 2018). "The ability of BFE to limit HGF-induced matrix adherence of the TNBC cancer cells was demonstrated through the attachment assay." (PMID 30314527, 2018). "HGF, produced by some cancer cells, stimulates c-Met, through activation of the autocrine signaling system." (PMID 30214428, 2018). "When there is a deletion of exon 14, the loss of Y1003 leads to c-Met accumulation on the cell surface and high HGF stimulation contributes to cancer progression." (PMID 30134579, 2018). "Intervention of NK4, HGF inhibitor or imatinib mesylate declined the cancer cells functions in the presence of osteoblast." (PMID 29455663, 2018). "HGF has pleiotropic activities both in normal and in cancer cells, and its role in cancer has been widely documented." (PMID 29558956, 2018). "The HGF-cMet pathway, involving the cross-talk between CAFs and cancer cells, plays a role in cancer metastasis, and is another potential target for blocking CAF–cancer cell interaction." (PMID 30380628, 2018). "A clear correlation between production of HGF and stimulation of cancer cell migration was observed." (PMID 29558956, 2018). "In this study, we demonstrate that TGFβ signaling leads to increased MET signaling activity and that this results in HGF‐dependent migration of breast epithelial and cancer cells." (PMID 30004628, 2018). "MET, a transmembrane tyrosine kinase receptor for hepatocyte growth factor (HGF), has been observed to contribute to cancer metastasis, resistance to chemotherapeutic agents, and dismal outcomes of patients with solid cancers including HCC." (PMID 29712569, 2018).
cancer (continued). "Dysregulated pro-HGF activation (with upregulated MET phosphorylation) is reported to promote cancer progression in various cancers." (PMID 30469509, 2018). "The binding of HGF to c-Met can initiate several downstream signaling pathways; we selected three significant pathways, based on their functions in carcinoma for futher review." (PMID 29455668, 2018). "hPSC secretions with known amounts of HGF (2000pg/mL) induced AsPC-1 proliferation compared to controls i.e. cancer cells incubated with co-culture medium alone, confirming our previously published studies." (PMID 29100344, 2017). "In U87MG (an HGF-dependent GBM cell line), IRCR201 showed more potent cancer cell growth inhibition compared to huOA5D5.v2, which has previously been reported to suppress only HGF-dependent cellular proliferation." (PMID 28902178, 2017). "In contrast, invasiveness of Ec.20 cells was not affected by the pro-longed interactions with RMF-HGF (CC.RMF-HGF), suggesting that EcSOD inhibits HGF-mediated invasion of cancer cells." (PMID 29296173, 2017). "For example, Our previous studies indicate that treatment of cancer cells with hepatocyte growth factor induced cancer stem cell phenotypes by increasing the expression of reprograming factors including KLF4." (PMID 28553926, 2017). "By impairing both HGF-dependent and c-Met-amplified downstream activation in various cancer types, IRCR201 is differentiated from other therapeutic antibodies by securing a wide range of drug response groups." (PMID 28902178, 2017). "HGF activates pro-survival signaling and promotes epithelial-mesenchymal transition of cancer cells, hindering the response to therapy." (PMID 28968967, 2017). "Previous studies have suggested that activated PSCs promote the invasion and metastasis of cancer cells in a paracrine manner via the secretion of soluble factors, such as stroma‐derived factor 1, hepatocyte growth factor, and other inflammatory factors." (PMID 28783244, 2017). "This indicates that the previously reported inhibitory effect of TGFβ on PSC-induced cancer cell migration involves HGF-dependent signaling." (PMID 29069737, 2017). "Increasing evidence indicates that hepatocyte growth factor (HGF) induces cancer cell migration and invasion." (PMID 28475121, 2017). "We demonstrated that HGF or HGF-producing fibroblasts conferred resistance to EGFR targeting therapy by reactivation of pro-survival pathways in cancer cells, including ERK and AKT activation." (PMID 28420162, 2017). "It has also been shown that hypoxia activates an invasive growth program orchestrated by hepatocyte growth factor (HGF) that leads cancer cells away from the hypoxic area, enabling them to escape anti-angiogenic therapy." (PMID 28445144, 2017). "Clinical trials targeting the c-Met axis in HNSCC have been undertaken because of significant preclinical work demonstrating a relationship between HGF/c-Met signaling and cancer cell survival." (PMID 29231907, 2017). "The definition of the high expression of HGF is still controversial under current circumstance, similar to other genes in cancer, such as the carcino-embryonic antigen in CRC." (PMID 28423584, 2017). "Aberrant activation of HGF/c-MET signalling by mutation, autocrine or paracrine HGF stimulation, or overexpression has been implicated in the oncogenesis of large number of cancers." (PMID 28511645, 2017). "c-Met has been shown to form a complex with integrin α6β4, therefore, enhancing HGF-induced cancer cell invasion." (PMID 28475121, 2017). "HGF dependence has emerged as a hallmark of therapeutic resistance, suggesting that inhibitors of biological activity of HGF should be included into therapeutic regimens of cancer patients." (PMID 28420162, 2017). "HGF/SF-mediated activation of MET causes cell proliferation, cell migration, and angiogenesis, all of which contribute to cancer progression." (PMID 28827556, 2017).
cancer (continued). "As a stroma-derived factor, HGF has been shown to be involved in cancer progression, especially in EMT, invasion, and metastasis." (PMID 28545495, 2017). "This antioxidant enzyme also inhibited HGF-mediated cancer-fibroblast interactions in our co-culture model." (PMID 29296173, 2017). "HGF promotes proliferation, migration, invasion and survival of cancer cells and confers resistance to therapy." (PMID 28420162, 2017). "Activation of the HGF/c-MET axis in cancer has been reported to be involved in cellular proliferation, survival, migration and angiogenesis." (PMID 28511645, 2017). "HGF/c-Met signaling has been intensively investigated for its role in cancer’s motility, invasion, metastasis, proliferation, and growth." (PMID 28475121, 2017). "Astrocytes secrete hepatocyte growth factor/scatter factor (HGF/SF) under the influence of cancer cell-derived IL1β." (PMID 29312881, 2017). "Based on these characteristics, c-Met and HGF have been considered as ideal therapeutic targets in cancer-specific treatments; thus, numerous pre-clinical studies targeting the HGF/c-Met axis have been reported." (PMID 28902178, 2017). "Supporting these results, are our in vitro observations whereby HGF inhibition or c-MET blockade alone inhibited cancer cell proliferation." (PMID 29100344, 2017). "It has been reported that HGF/c-Met triggers downstream phosphoinositide 3-kinase (PI3K)/Akt pathway to exert the effects on cancer progression." (PMID 28258248, 2017). "HGF showed an increased expression in cancer tissues compared to normal tissues, while miR-7 showed the opposite pattern, confirming the observations in previous studies." (PMID 29133945, 2017). "Another approach in targeted cancer gene therapy of solid tissues is based on local delivery of NK4 (hepatocyte growth factor antagonist) secreted from an NK4 gene-transduced oral mucosal epithelial cell." (PMID 28380080, 2017). "Taken together, our study shows that ROS contributes to HGF-stimulated c-Met activation and that overexpressing the extracellular antioxidant enzyme, EcSOD suppresses this oncogenic cancer-fibroblast interaction." (PMID 29296173, 2017). "This altered subpopulation contributes to cancer progression, with paracrine secretion of pro-cancer factors (e.g. HGF, TGFβ, VEGF, NK4), deposition and remodeling of the ECM and immune regulation." (PMID 29116016, 2017). "Supporting this notion, it has been shown that HGF is required for optimal activation of the MET kinase in MET amplified cancer cells." (PMID 28420162, 2017). "The interaction of HGF and c-Met further activates downstream signalling pathways to regulate cancer progression." (PMID 28258248, 2017). "We chose cardiac specific HGF overexpression, as other strain of HGF transgenic mice such as liver and kidney specific HGF overexpression mice develop cancer and cystic diseases, which are rare in the heart." (PMID 28273932, 2017). "We further determined the effects of EcSOD on HGF/c-Met-mediated cancer-fibroblast interactions by co-culturing normal fibroblasts (RMF) or RMF which overexpresses HGF (RMF-HGF) with MDA-MB231 cells." (PMID 29296173, 2017). "HGF/c-Met is important to both normative function and cancer biology, suggesting a value in appreciating both." (PMID 29231907, 2017). "Taken together, IRCR201 represents a promising therapeutic antibody to treat cancer patients suffering from dysregulation of the HGF/c-Met signaling pathway." (PMID 28902178, 2017). "Distinct heterodimers of integrins are regulated by HGF at the level of expression in different cancer cells." (PMID 28475121, 2017). "The prolonged survival of cancer cells induced by co-culture with fibroblasts was abolished in the presence of either anti-HGF neutralizing antibody or PHA-665752, a specific Met inhibitor." (PMID 28619066, 2017). "Cytoskeleton remodeling and reorganization have been shown to be the major molecular mechanisms of HGF-induced cancer cell migration and metastasis." (PMID 28475121, 2017).